IL10 (interleukin 10)
Diseases named in the same sentence as IL10 in open-access papers (continued):
Sharing a sentence is not in itself a finding about the gene and the disease.
experimental autoimmune encephalomyelitis (continued). "The first observation of regulatory function of B cells producing interleukin-10 (IL-10) was demonstrated in mice with experimental autoimmune encephalomyelitis in 1996 by Janeway and colleagues." (PMID 29403470, 2017). "B cells can regulate experimental autoimmune encephalomyelitis (EAE) via the production of interleukin-10 (IL-10)." (PMID 29201923, 2017). "Recently, we reported treatment targeting CD226 can ameliorate experimental autoimmune encephalomyelitis (EAE) by promoting IL‐10 expression via regulation of CD4+ T cell differentiation." (PMID 29299389, 2017). "Intranasal administration of this peptide prevents the induction of experimental autoimmune encephalomyelitis (EAE) in mice by induction of regulatory T cells which produced IL-10." (PMID 28455817, 2017). "For example, let-7e overexpression activates Th1 and Th17 cells and aggravates experimental autoimmune encephalomyelitis and Hashimoto’s disease by targetting IL-10." (PMID 28864780, 2017). "In agreement with our results, the suppression of Th1 and Th17 responses and attenuation of experimental autoimmune encephalomyelitis by F. hepatica was maintained in IL-10(-/-) mice, but was reversed by neutralization of TGF-beta in vivo." (PMID 25486609, 2014). "In fact, the transfer of human IL-10 or intracerebral injection of IL-10 significantly inhibit experimental autoimmune encephalomyelitis." (PMID 22438968, 2012). "Analysis of cytokine mRNA expression in the CNS of mice with experimental autoimmune encephalomyelitis reveals that IL-10 mRNA expression correlates with recovery." (PMID 20025765, 2009). "Similarly to our finding, CDDO-DFPA was found to upregulate the expression of TGF-β and IL-10 in DCs, resulting in the inhibition of T-cell responses in an experimental autoimmune encephalomyelitis (EAE) model." (PMID 41596216, 2026). "However, neutralizing IL-10 with an anti-IL-10 antibody eliminated the protective impact by MaR1 in relapsing-remitting experimental autoimmune encephalomyelitis model, implying the significance of IL-10 in MaR1 treatment." (PMID 39864620, 2025). "Hence, it has been reported that in VPAC2-deficient mice with experimental autoimmune encephalomyelitis, proinflammatory cytokines (TNF-α, IL-6, IFN-γ (Th1), and IL-17 (Th17)) increased, and anti-inflammatory cytokines (IL-10, TGF-β, and IL-4 (Th2)) decreased." (PMID 36101343, 2022). "The inhibitory effect of PPARD agonist was also found to be associated with an increase of cytokine IL-4 and IL-10 expression and decreased IL-12 and IL-23 expression in the CNS confirming the modulatory effect of PPARD agonist in experimental autoimmune encephalomyelitis." (PMID 34394070, 2021). "Plasmablasts in the draining lymph nodes negatively regulate experimental autoimmune encephalomyelitis, and IL10-producing B cells depend on dendritic cells to suppress antigen-specific CD8 T which can protect from type 1 diabetes in non-obese diabetic (NOD) mice." (PMID 34594327, 2021). "In this study, we showed that Cd226−/− mice were resistant to myelin oligodendrocyte glycoprotein peptide 35-55 (MOG35−55)-induced experimental autoimmune encephalomyelitis (EAE) with highly expressed IL-10+CD4+ T cells and downregulated IL-17A+CD4+ T cells when compared with wild-type (WT) mice." (PMID 32983109, 2020). "The reduction in BA concentration had previously been described in MS patients with chronic progressive disease, and both effector and IL-10+ T cells were shown to be induced by SCFAs and dietary fiber in experimental autoimmune encephalomyelitis (EAE), the animal model of MS." (PMID 32733460, 2020). "Moreover, silencing of miR-21 significantly alleviated the severity of experimental autoimmune encephalomyelitis (EAE), and this change was associated with an increase in the number of IL-10+ Breg cells." (PMID 29212210, 2017).
experimental autoimmune encephalomyelitis (continued). "Furthermore, IL-10 was shown to be essential for the protection of C57BL/6 mice from experimental autoimmune encephalomyelitis after administration of the soluble peptide 35–55 from myelin oligodendrocyte glycoprotein." (PMID 28455817, 2017). "Moreover, the MBP peptide 1–9 induced regulatory T cells of the Tr1 type in vivo, and neutralization of IL-10 prevented the peptide MBP from protecting against experimental autoimmune encephalomyelitis." (PMID 28455817, 2017). "Moreover, an increased expression of IL-10 in relation to enhanced neuronal levels of CD200 has been also found in the central nervous system of experimental autoimmune encephalomyelitis mice." (PMID 26891688, 2016). "It has been demonstrated that mice with levels of CD200 increased by spontaneous mutation in the Wld gene have less activated monocytes and increasing expression of IL-10 in the central nervous system following induction of experimental autoimmune encephalomyelitis." (PMID 26891688, 2016). "In vivo, IL-10 was identified as an essential component for vitamin D-mediated inhibition of experimental autoimmune encephalomyelitis and in vitro, vitamin D-induced IL-10-producing Tregs were able to prevent the induction of experimental autoimmune encephalomyelitis in an IL-10 dependent way." (PMID 25279717, 2014). "Notably, IL-10 suppresses IL-1 production and that IL-1 is involved in controlling Th17 cells in the mouse model of experimental autoimmune encephalomyelitis (EAE)." (PMID 22176654, 2011). "Furthermore, the recent study examined how the adoptive transfer of IL-10+ regulatory B cells (Bregs) in female mice with experimental autoimmune encephalomyelitis (EAE) can reverse the disease and promote the expansion of peripheral and CNS-infiltrating IL-10+ T cells." (PMID 37333618, 2023). "In THP-1-derived macrophages and experimental autoimmune encephalomyelitis mice, OLE reduced the levels of anti-inflammatory cytokines such as IL-10." (PMID 39940428, 2025). "In both experimental autoimmune encephalomyelitis (EAE) and collagen-induced arthritis (CIA), the differentiation of IL-10+ regulatory B cells is impaired as a result of HIF-1α deficiency." (PMID 39543372, 2025). "In experimental autoimmune encephalomyelitis (EAE), GA positively regulates inflammation by increasing anti-inflammatory IL-4, IL-10 and IL-13, while the pro-inflammatory cytokines IL-6, IL-12 and TNF-α are reduced." (PMID 36831209, 2023). "Nevertheless, the ability of DcR3 to upregulate IL-4 and IL-10 but simultaneously downregulate IFN-γ, IL-12, TNFα, and IL-17 after influenza hemagglutinin peptide stimulation and in the experimental autoimmune encephalomyelitis model was demonstrated." (PMID 33746978, 2021). "We have shown previously that treatment of Tg4 mice with soluble 4Y peptide led to protection from experimental autoimmune encephalomyelitis (EAE) that was both dose and IL-10 dependent." (PMID 33936079, 2021). "For example, in previous studies, GA was found to be protective against Experimental Autoimmune Encephalomyelitis (EAE) in Stat6–/– and IL4–/–IL10–/– mouse models." (PMID 34744620, 2021). "Estradiol has been reported to protect against development of experimental autoimmune encephalomyelitis (EAE) in mice by decreasing the production of inflammatory cytokines and increasing IL-10, and through expansion of Treg cells." (PMID 25826377, 2015). "Mice received T. spiralis MES simulated DCs significantly boosted Treg cells that secreted regulatory IL-10 and TGF-β cytokines, and decreased production of IFN-γ and IL-17 that leaded to the amelioration of experimental autoimmune encephalomyelitis." (PMID 24788117, 2014). "Evidence from animal study suggests that microbiota transplantation from patients with MS into germ-free(GF) mice validated exacerbated symptoms in experimental autoimmune encephalomyelitis (EAE) mice and a decreased ratio of IL-10+ regulatory T cells compared to controls." (PMID 39224586, 2024).
experimental autoimmune encephalomyelitis (continued). "A study in a model of experimental autoimmune encephalomyelitis in mice found that Hypericum perforatum extract in combination with gold nanoparticles decreased levels of IFN-γ, IL-17A and IL-6 and increased those of TGF-β, IL-10 and IL-4." (PMID 37687297, 2023). "Also, in experimental autoimmune encephalomyelitis (EAE), MZ B cells and Transitional B cells act as a source of both IL-6 and IL-10 cytokines." (PMID 34209841, 2021). "The expression of IKZF3 and IL-10 in nonpathogenic Th17 cells with a reduced capacity to drive experimental autoimmune encephalomyelitis has been previously noted." (PMID 32321757, 2020). "However, in the experimental autoimmune encephalomyelitis (EAE) model, apitope-induced tolerance was also mediated by IL-10 producing Foxp3-negative Tr1 cells, similar to what we think our mCTA1–T146 fusion protein does in the EAMG model." (PMID 28959261, 2017). "Functional studies in experimental autoimmune encephalomyelitis (EAE) indicate that B-cell deficiencies, and a lack of IL10 and IL35 leads to a poor prognosis." (PMID 27682872, 2017). "In line with our findings, CD200Fc treatment significantly decreased the production of TNF and IL-6 but not of IL-10 or TGF-β in microglial cells of mice with experimental autoimmune encephalomyelitis." (PMID 26891688, 2016). "This has been demonstrated in experimental autoimmune encephalomyelitis where wild-type mice spontaneously remit or even recover within 30 days, but mice with a selective lack of IL-10 expression in B cells fail to do so." (PMID 26016954, 2015). "This is similar to what was observed in rodent models of experimental autoimmune encephalomyelitis (EAE), where expression of IL-1β activated and translocated NF-ΚB to the nucleus and induced expression of inflammatory cytokines, IL-1β and TNF-α, as well as the IL-10." (PMID 38938553, 2024). "Additionally, we examined IL-10 impact on synaptic transmission in striatal medium spiny neurons and its role in counteracting inflammatory synaptopathy induced by IL-1β in female C57BL/6 mice with experimental autoimmune encephalomyelitis (EAE)." (PMID 39169949, 2024).
endometriosis (102 papers, 2009 to 2026). The growth of functional endometrial tissue in anatomic sites outside the uterine body. "Recently, altered levels of interleukin-24 (IL-24), a member of the IL-10 cytokine family also known as melanoma differentiation-associated gene-7 (mda-7), have been determined in the endometrium of women with endometriosis." (PMID 40607413, 2025). "Peritoneal fluid and serum of patients with advanced endometriosis stages show elevated content of Th2-associated cytokines IL-4 and IL-10 and reduced concentration of Th1 cytokines IFN-γ and IL-2 compared to healthy women." (PMID 41488658, 2025). "IL-24, a member of the IL-10 cytokine family, has also been implicated in the pathogenesis of endometriosis." (PMID 40607413, 2025). "One paper suggested that ectopic endometrial stromal cells secrete fractalkine (FKN), which increases the level of IL-10 but decreases the level of IL-2, causing M1 macrophages to shift to M2 to enhance the formation of endometriosis." (PMID 40747182, 2025). "The sensitivity and specificity of IL-10 as a standalone diagnostic marker for endometriosis are generally considered limited." (PMID 39767772, 2024). "In our study, we demonstrated that IL-8 and IL-10 can serve as a diagnostic and prognostic element of endometriosis, their value being directly proportional to the severity of endometriosis." (PMID 39202309, 2024). "Research using a mouse model of surgically induced endometriosis led the authors to conclude that changes in IL-10 concentration are associated with the growth of ectopic endometrial tissue." (PMID 39767772, 2024). "The increased concentration of IL-10 has been linked to the reduced cytotoxicity of NK cells observed in endometriosis, underscoring the concept that local cytokine dysregulation facilitates the implantation of endometrial fragments in the peritoneal cavity." (PMID 38928175, 2024). "IL-10, an anti-inflammatory cytokine associated with the M2 phenotype, is also elevated in women with endometriosis." (PMID 36555618, 2022). "An association of elevated IL-10 levels with reduced NK cell cytotoxicity in the endometriosis environment was also presented." (PMID 35805112, 2022). "Endometriosis was also associated with elevated concentrations of IL-6, IL-10, and TGF-β1/2 as well as CCL20, CXCL8, CXCL9, and CXCL10." (PMID 34501240, 2021). "The increased concentration of IL-10 has been implicated in the decreased cytotoxicity of NK cells observed in endometriosis and supports the notion that local cytokine dysregulation allows endometrial fragments to implant in the peritoneal cavity." (PMID 26247027, 2015). "IL-10 is reported to be increased in the peritoneal fluid and serum of women with endometriosis and increasing IL-10 has been linked to a decrease in CD4+ T lymphocyte activation and therefor decreased immune responses." (PMID 25207642, 2014). "For instance, promoter polymorphism of interleukin-10 gene (rs180087) was recently shown to be associated with the risk of endometriosis." (PMID 23139742, 2012). "For instance, measuring the number of imDC or even the cytokines produced by the DC, like IL-1β, IL-6, and IL-10, in the peritoneal fluid of patients with endometriosis might serve as a diagnostic tool." (PMID 40747182, 2025). "Dyspareunia in patients with endometriosis may be associated with IL-8, IL-10, and BDNF, as these biomarkers contribute to inflammatory and neurogenic processes that heighten pain sensitivity." (PMID 39796020, 2024). "Polymorphisms within the IL10 gene exhibit varying associations with endometriosis." (PMID 39767772, 2024). "A study in the Chinese population showed that the presence of polymorphisms 592A/C and 819T/C of the IL-10 promoter is associated with an increased risk of endometriosis and may be associated with increased disease progression." (PMID 37446108, 2023).
endometriosis (continued). "An elevated level of IL‐10 has been considered a critical factor for the development of endometriosis; however, its detailed mechanism and causal relationship remain unclear." (PMID 31418859, 2019). "The immunosuppressive cytokines TGF-β and IL-10 have been implicated in endometriosis." (PMID 25275597, 2014). "On the basis of the presence and activity of selected cytokines typical for various types of cellular response, it was indicated that the development of endometriosis is favored by Th2 cellular response and the associated cytokines, IL-4, IL-5, IL-6, IL-10 among others." (PMID 24298555, 2013). "The rs1800871 (-819C/T) SNP, located within the functional promoter of IL-10 gene, was found to affect in endometriosis both the mRNA and the protein levels of IL-10, with women of the TT genotype showing a 2-fold increased risk for developing endometriosis compared to “C” allele carriers." (PMID 40725086, 2025). "Recent studies show that sustained STAT3 activation promotes endometriosis fibrosis by enhancing IL-10 and IL-6 anti-inflammatory effects." (PMID 41170181, 2025). "Another study showed that the serum from endometriosis patients had higher levels of IL-10 and induced a tolerogenic DC phenotype in vitro." (PMID 40679648, 2025). "They contribute to the pathogenesis of endometriosis by secreting IL-10, a tolerogenic cytokine, which promotes the migration of ectopic endometrial tissue and promotes angiogenesis, protecting the ectopic endometrial tissue from immune clearance." (PMID 40747182, 2025). "Their regulatory abilities are linked to the secretion of inhibitory cytokines, such as IL-35, TGF-beta, and IL-10, all of which are dysregulated in endometriosis." (PMID 40607413, 2025). "A dysregulation of cytokines, including IL-17, IL-23, and IL-10, is common amongst these inflammatory diseases and endometriosis." (PMID 39596309, 2024). "IL-10’s role in immune modulation highlights its potential as a marker for immune response in endometriosis, guiding therapeutic strategies." (PMID 39202309, 2024). "Cytokines such as IL-37, IL-17A, IL-10, and IL-2 play essential roles in modulating immune responses in endometriosis." (PMID 39595927, 2024). "This study aims to investigate the possible relationship between sexual quality of life in patients affected by endometriosis and a series of biomarkers: interleukin 8 (IL-8), interleukin 10 (IL-10), and Brain-Derived Neurotrophic Factor (BDNF)." (PMID 39796020, 2024). "Our data show a high statistical significance between tissue expression of IL-8, IL-10, patient-related pain, and the severity of endometriosis." (PMID 39202309, 2024). "Higher levels of serum IL-37 and IL-10, and significantly lower levels of serum IL-17A and IL-2 were detected in patients with endometriosis." (PMID 39595927, 2024). "In particular, IL-10 plays a crucial role in endometriosis development, as its expression triggers the activation of MMPs, ECM remodelling, and angiogenesis in serum and peritoneal fluid." (PMID 38928175, 2024). "IL‐10 released from local plasmacytoid dendritic cells accelerates the development of endometriosis via pathological angiogenesis during the early disease stage." (PMID 39622780, 2024). "One article showed that interleukins IL-2 and IL-27 work together to enhance the growth and invasion of endometriotic stromal cells by regulating the balance between IFNγ and IL-10 in the context of endometriosis." (PMID 39767772, 2024). "Numerous studies have shown that IL-10 levels in both serum and peritoneal fluid are significantly increased in women with endometriosis compared to controls." (PMID 39767772, 2024). "For IL-8 and IL-10, the trend also persists, but with a relatively smaller increase compared to the endometriosis group." (PMID 39202309, 2024). "Decreasing IL-10 activity in mice with surgically induced endometriosis significantly reduced the size of endometrial lesions." (PMID 37446108, 2023).